CRP (C-reactive protein)
Diseases named in the same sentence as CRP in open-access papers (continued):
Sharing a sentence is not in itself a finding about the gene and the disease.
Sepsis (continued). "Another previous study found that PCT was better than CRP in a group of adult patients, with AUCs of 0.925 vs 0.677 for the diagnosis of sepsis." (PMID 28764651, 2017). "As regards the primary end points of this study, we found 98.03% sensitivity and 91.0% specificity of CRP in confirming the diagnosis of sepsis in neonates after 72 hours of admission." (PMID 29492073, 2017). "In present study, we evaluated the adequacy of serum CRP in diagnosing neonatal sepsis and their role in determining the duration of antibiotic treatment in neonates presenting with suspicion of septicemia." (PMID 29492073, 2017). "The ROC analysis showed that hs-CRP was a good marker for the discrimination of sepsis/SS patients, with an area under the curve (AUC) of 0.825 (95% confidence interval[CI]: 0.73-0.92; P<0.001)." (PMID 28764651, 2017). "Among the various hematological factors studied for the early diagnosis of sepsis, CRP is one of them and is most widely studied." (PMID 29492073, 2017). "In comparison, elevated levels of CRP on day 1 and day 2 and of PCT from day 0 to day 2 were associated with the development of severe sepsis." (PMID 28845081, 2017). "Blood was collected 24 hours before and after surgical intervention for determination of the sepsis biomarkers suPAR, CRP, PCT, and IL-6." (PMID 30671318, 2016). "Clinical signs of sepsis included increased body temperature, neutrophilia, increased C-reactive protein (CRP) and interleukin-6 (IL-6), and decreased serum iron." (PMID 26879530, 2016). "Based on these characteristics, the availability of PCT immunoassays lessened the importance of CRP as a biomarker of sepsis." (PMID 27256181, 2016). "Patients presenting with sepsis or fever, immunosuppressed or frail patients, those with higher C reactive protein (CRP) or WCC at admission, and those who had received community antibiotic therapy were more likely to start antibiotics in hospital." (PMID 27554101, 2016). "Increasing CRP concentrations have been shown to be useful for the detection of sepsis or organ dysfunction, whereas a rapid decrease in CRP level has been reported to be one of the earliest markers of improvement." (PMID 27182730, 2016). "Univariate logistic regression showed that age, gender, CRP, PCT and SOFA were risk factors for occurrence of sepsis." (PMID 27287669, 2016). "Another limitation is inability to use other inflammatory markers as IL-6 and TNF-alpha besides CRP in comparison to PSP for early sepsis diagnosis." (PMID 27689072, 2016). "Five hours after the procedure the patient died of hepatic and renal failure with total metabolic collapse and sepsis (C-reactive protein: 420, Leukocytes: 29 × 10.8 × 109/L, Hemoglobin: 82 g/L, pCO2: 6, 08, and lactate: 13.2 mmol/L)." (PMID 26904354, 2016). "Despite all values being <50 mg/L (threshold for severe infection), there was a minor trend towards increased CRP levels in patients with a history of sepsis." (PMID 27056672, 2016). "Sixty-five patients with bacteremic sepsis had significantly higher C-reactive protein, white blood cell counts, and longer hospital stay than 49 ER controls." (PMID 26800189, 2016). "In the sepsis group, CRP levels measured on day 1 of admission to the ICU were 11.4±2.2 ng/ml (n = 24)." (PMID 27089280, 2016). "The aim of this study was to investigate the CRP and hemogram parameters as an indicator of sepsis diagnosis." (PMID 26863002, 2016). "Some researchers have tried to improve the prognostic accuracy of MEDS by combining it with sepsis biomarkers such as C-reactive protein, procalcitonin, and interleukin-6, with encouraging results." (PMID 27077648, 2016). "New sepsis guidelines propose monitoring of CRP and serum cytokines to aid in the diagnosis of sepsis in critically-ill patients in the ICU." (PMID 28469676, 2016). "Sepsis was indicated by increased body temperature (onset at 30 h PI), bacteraemia, and neutrophilia, together with increased IL-6, CRP, SAA, and decreased iron." (PMID 26879530, 2016).
Sepsis (continued). "In this study copeptin is shown to be superior to CRP in distinguishing the population of patients diagnosed with septic shock from those diagnosed with sepsis." (PMID 27366743, 2016). "In this study, the impact of tissue damage due to surgical interventions on the sepsis biomarkers suPAR, CRP, PCT, and IL-6 in patients treated for culture-proven bloodstream infection was investigated." (PMID 30671318, 2016). "As for the other inoculated pigs, sepsis was indicated by increased body temperature (onset at 15 and 22 h, respectively), bacteraemia, and neutrophilia, together with increased IL-6, CRP, SAA, and decreased serum iron." (PMID 26879530, 2016). "This is represented by high CRP, low HbA1c and high HOMA-IR in sepsis and lower CRP, high HbA1c and high HOMA-IR in T2D." (PMID 26873079, 2016). "In a pediatric study, the AUC for PCT was 0.99 compared to 0.54 for CRP to differentiate patients with SIRS from those with sepsis." (PMID 27089280, 2016). "IL-6 and CRP are the most common markers aimed at determining the inflammatory response to the HepB vaccine in infants in order to prevent sepsis or other severe adverse reactions after injection." (PMID 27022211, 2016). "Conservative management is preferable; however, in cases involving elevated CRP or WBC levels as well as signs of sepsis, bowel perforation, or free gas near the portal vein, immediate surgery is indicated." (PMID 27495256, 2016). "To compare these measures against an established biomarker we examined the correlation for each with C-reactive protein (CRP) for the sepsis cohort." (PMID 27089280, 2016). "Although several new markers of infection have been investigated recently, some studies suggested that CRP is still a significant, sensitive, and specific acute-phase protein for the prediction of sepsis especially in the developing countries." (PMID 27689072, 2016). "Another study showed that Presepsin was better than IL6, CRP and PCT in assessing the risk of death within 30 days after onset of sepsis." (PMID 27389015, 2016). "PCT has also been used as an indicator of sepsis and bacteremia in children withcancer and febrile neutropenia, and its accuracy in some studies is better thanthat of CRP." (PMID 28099644, 2016). "For example, in a clinical ICU setting the measurement of CRP is now included in the surviving sepsis campaign international guidelines as a component of the diagnosis of sepsis." (PMID 28469676, 2016). "In accordance with our results, CRP levels were observed to correlate with fatal outcome in sepsis and in severe community acquired pneumonia." (PMID 27182730, 2016). "A metaanalysis showed a moderate ability of PCT to diagnose sepsis in adult patients (AUC for PCT 0.78 vs CRP 0.71)." (PMID 27089280, 2016). "Recently, PCT and CRP can predict and identify patients for suspected sepsis in an emergency department." (PMID 27462492, 2016). "The level of CRP can increase significantly during acute inflammation, but its specificity for sepsis diagnosis is relatively low9." (PMID 27991579, 2016). "On admission, the patient was in a severe condition with sepsis (C-reactive protein: 342, Leukocytes: 21 × 10.8 × 109/L, and Hemoglobin: 68 g/L)." (PMID 26904354, 2016). "The present study identified that there were clear statistical differences between sepsis and trauma with similar clinical severities in subjects of CRP, fibrinogen, FDP, DD, and amplitude of blood clot in FIBTEM test." (PMID 27495106, 2016). "The CRP/ALB ratio was primarily investigated for the purpose of predicting mortality in patients with sepsis." (PMID 27812440, 2016). "Among the 344 neonates admitted with suspected cases of sepsis, the CRP level was measured in 326 cases where it was positive (>6 mg/L) in 278 (85.3%) cases." (PMID 26146621, 2015). "This study aimed to characterize the NICU patients with normal or low CRP levels at the onset of sepsis and compared them with other neonates who had an elevated CRP level." (PMID 26259626, 2015).
Sepsis (continued). "In this study, the CRP/albumin ratio at admission was positively correlated with the prognosis in severe sepsis and septic shock patients treated with EGDT." (PMID 26158725, 2015). "The CRP level was a predictor of sepsis-attributable mortality (OR 3.09, 95 % CI 1.50–6.37) in the high CRP group compared to the low CRP group." (PMID 26259626, 2015). "Data from adults suggest that higher CRP level predicts death in patients with bacteremia and/or sepsis." (PMID 25909192, 2015). "In conclusion, the CRP/albumin ratio is an independent predictor of long-term mortality in patients with severe sepsis or septic shock." (PMID 26158725, 2015). "The sepsis-attributable mortality rate was lower in the low CRP group (4.9 %) than in the high CRP group (13.6 %)." (PMID 26259626, 2015). "A considerable proportion of neonatal BSIs had a normal or low initial CRP level (≤10 mg/L), which was more likely to occur in low birth weight or extremely preterm infants, those with earlier onset of sepsis, and those infected with CoNS." (PMID 26259626, 2015). "Low birth weight neonates, very low gestational age infants, and those in whom the occurrence of BSI episodes occurred earlier in life were more likely to have normal CRP at the onset of clinical sepsis." (PMID 26259626, 2015). "Admission for sepsis and positive CRP increase the expected number of days on antibiotics by some 46% and 48%, respectively." (PMID 25946927, 2015). "In our study, the end point was 180-day mortality and the significance of CRP was evaluated as a prognostic factor in severe sepsis and septic shock patients." (PMID 26158725, 2015). "We investigated changes in PCT and CRP concentrations in critically ill patients with sepsis to determine which biochemical marker better predicts outcome." (PMID 26367532, 2015). "Many biomarkers, particularly procalcitonin (PCT) and C-reactive protein (CRP), are widely used to identify sepsis in current clinical practice." (PMID 26357898, 2015). "We investigated predictive values based on changes in PCT and CRP concentrations in critically ill patients with severe sepsis/septic shock to determine which biochemical marker better predicts outcome." (PMID 26367532, 2015). "Although beneficial effects of CRP have been reported, other studies showed initial PCT concentrations or changes in PCT concentration have higher prognostic value than CRP in sepsis." (PMID 26367532, 2015). "In the clinical sepsis group three infants (30.0%) had an increased CRP and one infant (10.0%) an increased IL-6." (PMID 25894336, 2015). "Approximately one-fourth of the cases of neonatal BSI—which is a surprisingly high proportion in the current cohort—had a CRP level of ≤ 10 mg/L at the onset of clinical sepsis." (PMID 26259626, 2015). "Plasma levels of interleukin 6, CRP, and procalcitonin reached their peaks on Day 0 (onset of sepsis) or Day 1 and declined rapidly thereafter despite the persistent severity." (PMID 26161427, 2015). "The CRP/albumin ratio was an independent predictor of mortality in patients with severe sepsis or septic shock." (PMID 26158725, 2015). "The number of WBCs and the concentration of CRP were similar in patients with definite sepsis, those with possible sepsis and those with N-I SIRS." (PMID 25887201, 2015). "Neonates in the high CRP group had a significantly higher sepsis-attributable mortality compared with those in the intermediate and low CRP groups (P < 0.05 by log-rank test)." (PMID 26259626, 2015). "In many centers only one CRP test is done on admission and if it comes out to be negative antibiotics are stopped and later on baby comes back with severe sepsis." (PMID 26150837, 2015). "The ROC curves were performed to assess the value of APACHE II score, CRP, and blood lactate on predicting hypoalbuminemia in sepsis." (PMID 26557421, 2015).
Sepsis (continued). "Our study shows that the CRP/albumin ratio at admission can be used as an independent predictor of 180-day mortality in patients with severe sepsis or septic shock." (PMID 26158725, 2015). "In contrast to the patients with sepsis, patients with chronic rheumatism presented a significant lower elevation of inflammatory markers such as CRP, leukocyte count, IL-6 and IL-10 (P<0.05) reflecting the moderate inflammatory condition." (PMID 25893429, 2015). "Il serait plus judicieux ultérieurement d'effectuer l’étude sur une population plus importante de patients et de de voir la contribution de la gravité ou du sepsis dans l’élévation de la CRP." (PMID 26301005, 2015). "Moderate evidence supports utilizing serum CRP as a biomarker for diagnosing acute appendicitis with sepsis; or as a potential indicator for predicting complications (abscess, anastomotic leaks) after major abdominal surgery." (PMID 26502877, 2015). "As per results of the study, CRP cannot be regarded as a good screening test for early diagnosis of sepsis but can be made part of a scoring system." (PMID 26150837, 2015). "Decisive moment in establishing diagnosis was the CRP value, which was significantly elevated and led on-call staff suspect abdominal complications and sepsis." (PMID 26557396, 2015). "Procalcitonin (PCT) and C-reactive protein (CRP) are the most frequently used biomarkers for critically ill patients with sepsis." (PMID 26367532, 2015). "The administration of midazolam alone or in combination with fentanyl markedly downregulated the expression of CRP, indicating inhibition of the inflammatory response in sepsis." (PMID 25780458, 2015). "The overall sepsis-attributable mortality rate was 7.4 % and occurred in 4.9, 6.6, and 13.6 % in the low, intermediate, and high CRP groups, respectively." (PMID 26259626, 2015). "In a recent study that evaluated the relevance of ultrasensitive CRP and PCT levels in patients after HSCT, it was verified that the ultrasensitive CRP was higher in the patients with aGVHD and also in the cases of sepsis." (PMID 26543528, 2015). "Episodes of BSI with concurrent meningitis, ventilator-associated pneumonia, and catheter-related BSI also had elevated CRP at the onset of clinical sepsis." (PMID 26259626, 2015). "Along with clinical evidence of the disease, CRP provides good idea regarding septicaemia diagnosis." (PMID 26150837, 2015). "Although a lot of works indicate that both PCT and CRP are two superior markers for diagnosis of sepsis and infection, we suggest here the TNF-α is also a promising marker in NS." (PMID 24672322, 2014). "Factors found to predict neonatal septicaemia were positive CRP (p < 0.001, 95% CI; 2.6-8.2), elevated WBC (p < 0.001, 95% CI; 1.03-1.08), high body temperature (p = 0.04, CI 1.01-1.32) and home delivery 95% CI; 2.29(1.05-5.01)." (PMID 25280754, 2014). "In patients with suspected severe sepsis and septic shock, precipices reveals valuable diagnostic capacity to differentiate sepsis severity compared to PCT, IL-6, CRP, WBC." (PMID 25190134, 2014). "SAA concentrations were significantly increased in septic dogs which points to a possible higher clinical value for SAA in the detection of sepsis compared with CRP, and this potential deserves to be further investigated." (PMID 25430894, 2014). "PCT best predicted septicemia when compared with IL-6 and CRP with 73% sensitivity and 70% specificity for bacteremia with a cutoff of 0.5 ng/mL." (PMID 24772418, 2014). "Serum cytokine levels and CRP in the control group and patients with sepsis or intracranial infection." (PMID 24887408, 2014). "The hematologic profiles of the suspected sepsis group were characterized by higher white blood cell count, neutrophil counts and C-reactive protein." (PMID 25033045, 2014). "In the present study, the overall sensitivity and specificity of CRP in the diagnosis of neonatal septicaemia were 63% and 73% respectively." (PMID 25280754, 2014).
Sepsis (continued). "The patients admitted to ICU often delayed more than 24 hours, either CRP or cytokines serum concentration was unable to reach the peak at the period of sepsis." (PMID 24672147, 2014). "There is variation in the performance of CRP in the diagnosis of septicaemia depending on the etiology of septicaemia and the setting." (PMID 25280754, 2014). "To date, CRP and PCT have been proposed for inclusion as two mostly used diagnostic markers in the international definition of sepsis." (PMID 24672322, 2014). "As analyzed above, CRP and the three cytokines IL-2, IL-6 and IL-10 were differentially related to sepsis and intracranial infection." (PMID 24887408, 2014). "For all neonates in whom sepsis was suspected, screening tests including complete blood count, CRP, and micro erythrocyte sedimentation rate (ESR), blood culture, urine culture, cerebrospinal fluid (CSF) analysis and culture were performed." (PMID 25793056, 2014). "It is known that PCT and CRP are useful in the diagnosis of bacterial infection and sepsis, but with limitations." (PMID 24669245, 2014). "This meta-analysis showed that the summary receiver operating characteristics curve for PCT was higher than for CRP for identification of sepsis (0.78 versus 0.71, P = 0.02)." (PMID 24800240, 2014). "Empirical treatment was initiated for refractory fever (39 %), recurrent fever (48 %), clinical signs of sepsis (5 %) and tachycardia with elevated C-reactive protein (CRP) (4 %)." (PMID 24026863, 2014). "CRP has been used successfully during initial sepsis diagnosis, but its specificity is further reduced later in the course due to persistently elevated levels." (PMID 24772418, 2014). "The area under the ROC curve for MMP-8 in the diagnosis of sepsis was 0.87 (95% CI 0.82–0.92), and that of CRP was 0.98 (0.94–0.998), whereas the area of MMP-9 in the detection of non-septic state was 0.73 (0.65–0.80), p < 0.0001 for all curves." (PMID 24833564, 2014). "C-reactive protein (CRP) is an extensively utilized biomarker for monitoring sepsis, post-surgical complications, and inflammation in the pediatric and neonatal populations." (PMID 25485262, 2014). "The white blood cell count, neutrophil count and CRP were significant higher in suspected sepsis neonates compared with the corresponding values of controls (P = 0.018, 0.007 and 0.003, respectively)." (PMID 25033045, 2014). "ESR and CRP have been known for a long time to be elevated in inflammatory conditions, including infection, and were used widely as an adjunctive test in sepsis and have often been used as a comparator for newer biomarkers." (PMID 24772418, 2014). "Presepsin levels had valuable diagnostic value for the diagnosis of sepsis, severe sepsis and septic shock at days 1, 3 and 8 of ICU treatment compared to PCT, IL-6, CRP and WBC." (PMID 25190134, 2014). "We determined the accuracy of Rubarth’s newborn scale of sepsis and C- reactive protein in diagnosing neonatal sepsis and assessed antimicrobial susceptibility pattern of etiological bacteria." (PMID 25475836, 2014). "C-reaction protein (CRP), hematologic parameters, and cytokines have been used to identify accurately neonates with sepsis." (PMID 25033045, 2014). "In a study that included 68 critically ill patients, diagnosis accuracy of the eosinophil count for sepsis identification was similar to that of CRP or PCT." (PMID 24903083, 2014). "Presepsin levels revealed valuable diagnostic capacity to diagnose severe sepsis and septic shock at days 1, 3 and 8 (range of diagnostic area under the curves (AUC) 0.72 to 0.84, P = 0.0001) compared to IL-6, PCT, CRP and WBC." (PMID 25190134, 2014). "Another study using quantitative CRP assay should be considered in our setting in order to estimate the cutoff point of CRP which strongly predicts neonatal septicaemia." (PMID 25280754, 2014).